ENSG00000285558 (novel protein)
Gene: Protein-coding gene on chromosome 3 (141,738,474 to 141,807,919, forward strand). Ensembl gene ENSG00000285558.
Genetic constraint (gnomAD): Missense variants: 29 observed, 42.23 expected, observed/expected ratio (o/e) 0.69, 90% interval 0.51 to 0.94. Synonymous variants: 15 observed, 13.55 expected, observed/expected ratio (o/e) 1.11, 90% interval 0.74 to 1.68.